RNH1 (ribonuclease/angiogenin inhibitor 1)
Description:
Ribonuclease inhibitor which inhibits RNASE1, RNASE2 and angiogenin (ANG). May play a role in redox homeostasis. Required to inhibit the cytotoxic tRNA ribonuclease activity of ANG in the cytoplasm in absence of stress. Relocates to the nucleus in response to stress, relieving inhibition of ANG in the cytoplasm, and inhibiting the angiogenic activity of ANG in the nucleus.
Synonyms: RAI; RNH; IIAE12
Tractability: Small molecule: a structure with a bound ligand is known. Antibody: its Gene Ontology location is reachable by antibodies, with medium confidence. PROTAC: ubiquitination databases record sites on it; its protein half-life has been measured.
Gene: Protein-coding gene on chromosome 11 (494,510 to 507,300, reverse strand). Ensembl gene ENSG00000023191.
Subcellular location: Cytoplasm; Nucleus
Subcellular location (Human Protein Atlas): Cytosol; Nucleoplasm
Gene Ontology:
Molecular function: protein binding; ribonuclease inhibitor activity
Biological process: regulation of angiogenesis; tRNA stabilization; cell migration; mRNA catabolic process; regulation of Arp2/3 complex-mediated actin nucleation
Cellular component: angiogenin-PRI complex; cytoplasm; cytosol; extracellular exosome; nucleoplasm; nucleus; lamellipodium; plasma membrane
Genetic constraint (gnomAD): Loss-of-function variants: 39 observed, 43.59 expected, observed/expected ratio (o/e) 0.89, 90% interval 0.69 to 1.17. The upper end of that interval is the gene's LOEUF score, 1.17, which puts it in group 5 of 6, group 1 being the genes least tolerant of losing a copy. Missense variants: 577 observed, 585.58 expected, observed/expected ratio (o/e) 0.99, 90% interval 0.92 to 1.06. Synonymous variants: 319 observed, 278.13 expected, observed/expected ratio (o/e) 1.15, 90% interval 1.05 to 1.26.
Homologues: Orthologues: chimpanzee RNH1 (99% identical), pig RNH1 (76% identical), rat Rnh1 (74% identical), mouse Rnh1 (73% identical), dog RNH1 (71% identical), guinea pig RNH1 (67% identical), Drosophila melanogaster LRR (22% identical), Caenorhabditis elegans crml-1 (20% identical). Paralogues in human: CARMIL2 (25% identical), CARMIL1 (24% identical), CARMIL3 (24% identical), PPP1R37 (14% identical).
Diseases named in the same sentence as RNH1 in open-access papers:
RNH1 is named in the same sentence as 40 diseases in open-access papers, as found by Europe PMC text mining. Sharing a sentence is not in itself a finding about the gene and the disease. The quoted sentences say what the papers report.
breast carcinoma (6 papers, 2016 to 2024). "Among the identified proteins, RNH1, which has been reported to regulate the expression of mTOR in breast cancer, was of interest." (PMID 39513392, 2024). "When we analyzed the copy number variations of RNH1 in patient samples from 2 breast cancer TCGA data sets (TCGA, Cell and Firehose Legacy), we found the copy number amplification was significantly higher in BRCA2-low; MLH1-low human breast cancer samples compared with unaltered controls." (PMID 38271119, 2024). "LncRNA BDNF-AS was reported to promote breast cancer progression by functioning as a scaffold RNA, supporting RNH1 ubiquitination by the E3 ligase TRIM21 and thus RNH1 degradation." (PMID 33182489, 2020). "An in‐frame HRAS fusion gene was identified in a head and neck primary tumour (RNH1–HRAS) that leads to increased levels of HRAS expression 66; however, no additional HRAS fusion genes were detected in primary breast cancers." (PMID 27512948, 2016).
bladder cancer (5 papers, 2014 to 2025). "LC1 tumours also showed modest enrichment for immune‐associated transcripts, including CCL15 and PSMB10, and elevated RNH1 expression, a gene previously linked to reduced invasion and metastasis in bladder cancer." (PMID 41425537, 2025). "RNH1 encodes a ribonuclease inhibitor that has been reported as being aberrantly expressed in bladder cancer." (PMID 41226303, 2025). "Notably, RNH1 was also upregulated; lower expression of this gene has been associated with increased invasion and metastasis in bladder cancer, suggesting a protective role in this context." (PMID 41425537, 2025). "X Yao, D Li, DM Xiong, L Li, R Jiang and JX Chen reported that RNH1 suppressed the progression of bladder cancer by regulating epithelial-mesenchymal transition (EMT)." (PMID 38783241, 2024). "Downregulation of RNH1 increased cell proliferation, migration and invasion, promoted tumorigenesis and metastasis in bladder cancer in vivo, and altered cell morphology and adhesion by inducing the EMT signaling pathway in bladder cancer cells." (PMID 38783241, 2024). "RNH1 regulates the reactive oxygen species contribution to drug resistance in gastric cancer and the growth and metastasis of bladder cancer." (PMID 25058392, 2014). "RNH1 is lowly expressed in colorectal cancer and bladder cancer." (PMID 38783241, 2024).
gastric cancer (4 papers, 2014 to 2022). A primary or metastatic malignant neoplasm involving the stomach. "Additionally, RNH1 is highly expressed in histone deacetylase inhibitor resistant gastric cancer cell lines." (PMID 36503519, 2022). "RNH1 is reported to be a regulator of HDACi resistance, inducing drug resistance in gastric cancer." (PMID 28938550, 2017). "Our research found NAIF1 inhibits the expression of RNH1, which suggests that NAIF1 may collaborate with chemotherapy drugs in the clinical treatment of gastric cancer." (PMID 24926661, 2014).
Sepsis (4 papers, 2020 to 2024). Sepsis is defined as life-threatening organ dysfunction caused by a dysregulated host response to infection. "Since sepsis is strongly associated with multi-organ failure, we investigated the role of RNH1 in several organ functions." (PMID 38951571, 2024). "This suggests elevated RNH1 as a potential early indicator of sepsis-associated liver dysfunction." (PMID 38951571, 2024). "Thus, we investigated the role of RNH1 in sepsis-associated HAMP secretion." (PMID 38951571, 2024). "Generally, there is a paucity of knowledge regarding the physiological and pathophysiological role of RNH1 in sepsis." (PMID 38951571, 2024). "In conclusion, our study demonstrates that (a) the plasma dynamics of RNH1 have significant potential as a biomarker for adverse outcomes in sepsis, including mortality and renal and hepatic dysfunction, underscoring its prognostic value in septic patients." (PMID 38951571, 2024). "Future research needs to further explore these relationships and the mechanistic pathways to potentially integrate RNH1 into clinical practice in the future and thus improve sepsis treatment." (PMID 38951571, 2024). "Since bilirubin is the result of heme degradation by HMOX-158, it provides a link between our clinical observations and our ex vivo experiments, suggesting that RNH1 levels play a crucial role in iron homeostasis during sepsis." (PMID 38951571, 2024). "On day 7 after sepsis diagnosis, we observed a correlation between RNH1 levels and bilirubin levels on day 7 (p = 0.0361, r = 0.4488)." (PMID 38951571, 2024). "The fact that bilirubin is the result of heme degradation by HMOX-1 provides a link between our clinical observations and our ex vivo experiments, suggesting that RNH1 level play a crucial role in iron homeostasis during sepsis." (PMID 38951571, 2024). "To further investigate the as yet unknown role of RNH1 in sepsis, we analyzed its effect as a stimulus on the inflammatory response to LPS ex vivo." (PMID 38951571, 2024). "Therefore, our data contribute significantly to increasing the understanding of RNH1’s role in sepsis." (PMID 38951571, 2024). "However, nothing is yet known about the role of RNH1 as a potential biomarker or therapeutic target in sepsis." (PMID 38951571, 2024). "Beyond sepsis, RNH1 has been identified as a potential biomarker in various cancer." (PMID 38951571, 2024). "On the basis of these findings, RNase 1 and RNH1 serum levels may have the potential to predict post-operative sepsis, and thus the length of a hospital stay." (PMID 33066382, 2020). "However, RNH1 levels may play a central role in iron homeostasis during sepsis, supporting our clinical observations." (PMID 38951571, 2024). "Hence, we investigated RNH1 dynamics in patients on days 1–3, 5, and 7 after sepsis diagnosis." (PMID 38951571, 2024). "Our single-cell sequencing data demonstrated that sepsis marker genes were highly elevated in CD16+ monocytes, including NAP1L1, CFD, BID, BCL2A1, MALAT1, RNH1, and LILRA5 genes." (PMID 39294473, 2024). "Since macrophages are crucial players during the immune response to sepsis and known to be involved in the LPS-induced non-canonical inflammasome response, we examined the role of RNH1 in LPS-induced inflammation and non-canonical inflammasome activation in THP-1 macrophages." (PMID 38951571, 2024). "Furthermore, we explore RNH1 as a therapeutic target in sepsis-related processes like inflammation, non-canonical inflammasome activation, and iron homeostasis." (PMID 38951571, 2024). "However, further studies are warranted to understand the molecular details of how RNH1 regulates the priming and activation signal of the NLRP3 inflammasome and how these mechanisms are dysregulated in human inflammatory diseases, including COVID-19 and sepsis." (PMID 35256513, 2022).
Sepsis (continued). "The persistently elevated RNH1 levels observed from day 3 onwards, despite no significant changes over time, could indicate an ongoing inflammatory response or a balance between pro- and anti-inflammatory reactions, which is characteristic of the later stages of sepsis." (PMID 38951571, 2024). "Thus, the attenuating effect of RNH1 on LPS-induced relative FTH1 and HAMP mRNA expression and/or secretion may enhance rather than counteract sepsis." (PMID 38951571, 2024).
anemia (3 papers, 2021 to 2024). A reduction in the number of red blood cells, the amount of hemoglobin, and/or the volume of packed red blood cells. "RNH1 knock-out mice were reported to die from anemia caused by failed erythroid cell maturation due to deficient translation of the transcription factor GATA1." (PMID 36935417, 2023). "Similarly, deletion of RNH1 in mouse hematopoietic cells was found to dysregulate hematopoiesis and cause anemia." (PMID 38820160, 2024). "Moreover, mutations in the RNH1 gene in human have also been associated with anemia phenotype." (PMID 38820160, 2024). "In conclusion, we describe two siblings with a homozygous loss-of-function variant in RNH1 associated with a disorder characterized by congenital cataracts, global developmental delay, myopathy and infection-induced episodic psychomotor deterioration, seizures, and anemia." (PMID 36935417, 2023). "Mice knockout for Rnh1 die in utero during embryonic stage E8.5-E10 due to impaired development of the hematopoietic system and anemia." (PMID 36935417, 2023). "Surprisingly, we found that complete RNH1 deletion is embryonically lethal and mice died in utero during embryonic stage E10 due to anemia." (PMID 33525475, 2021). "Interestingly, RNH1-KO mice show severe decrease in the erythroid cells (anemia) as well as reduced polysomes." (PMID 33525475, 2021). "RNH1-KO mice died in utero due to impaired development of hematopoietic system and anemia." (PMID 33525475, 2021).
acute kidney injury (2 papers, 2020 to 2024). Sudden and sustained deterioration of the kidney function characterized by decreased glomerular filtration rate, increased serum creatinine or oliguria. "In clinical observations of patients undergoing thoracoabdominal aortic aneurysm (TAAA) repair, we previously identified RNH1 as a potential biomarker for acute kidney injury (AKI) and in-hospital mortality." (PMID 38951571, 2024).
cholangiocarcinoma (2 papers, 2016 to 2024). A carcinoma that arises from the intrahepatic biliary tree (intrahepatic cholangiocarcinoma) or from the junction, or adjacent to the junction, of the right and left hepatic ducts (hilar cholangiocarcinoma). "RNH1 has been reported as a potential biomarker for cholangiocarcinoma due to high autoantibody levels." (PMID 38783241, 2024).
glioma (2 papers, 2019 to 2023). A benign or malignant brain and spinal cord tumor that arises from glial cells (astrocytes, oligodendrocytes, ependymal cells). "PTEN negatively regulates miR-21 expression via the RNA-regulatory protein ribonuclease/angiogenin inhibitor 1 (RNH1), thereby preventing the downregulation of Spry2 by miR-21 in glioma cells." (PMID 32038175, 2019). "We observed the highest RNH1 alteration frequency among patients with seminoma, followed by glioma." (PMID 37537337, 2023).
cholangitis (1 paper, 2014). An acute or chronic inflammatory process affecting the biliary tract. "Plasma levels of ENO1 and RNH1 autoantibodies in cholangitis were significantly higher compared to healthy individuals (P<0.01)." (PMID 25058392, 2014). "Diagnostic performance of autoantibodies against HSP70, RNH1 and ENO1 in pairwise comparisons between CCA, cholangitis, or healthy controls." (PMID 25058392, 2014). "Anti-HSP70, ENO1 and RNH1 autoantibodies levels could be distinguished between healthy controls and cholangitis (P<0.01, AUC = 0.8170, 0.8043 and 0.7790, respectively)." (PMID 25058392, 2014). "In addition, circulating ENO1 and RNH1 autoantibodies levels were also significantly higher in cholangitis and CCA compared to healthy controls (P<0.05)." (PMID 25058392, 2014). "Further, plasma ENO1 and RNH1 autoantibodies were higher in CCA compared to cholangitis but failed to reach statistical significance." (PMID 25058392, 2014).
conduct disorder (1 paper, 2020). A disorder diagnosed in childhood or adolescence age group characterized by aggressive behavior, deceitfulness, destruction of property or violation of rules that is persistent and repetitive, and within a one year period. "Moreover, previous studies have reported that patients with 11p15.5 and 20q13.33 deletions, which include mutations in RNH1, had conduct disorder (CD), ADHD, and intellectual disabilities." (PMID 33374967, 2020).
congenital cataracts (1 paper, 2023). "Here, we report a family with two siblings carrying a bi-allelic null variant in RNH1 with a disease characterized by global developmental delay, muscle weakness and congenital cataracts." (PMID 36935417, 2023). "In our patients this hypothesis may be relevant and related to the congenital cataracts associated with lack of RNH1, although the mechanisms remain elusive." (PMID 36935417, 2023).
COVID-19 (1 paper, 2022). A disease caused by infection with severe acute respiratory syndrome coronavirus 2. "Collectively, our findings suggest that decreased expression of RNH1 associated with severity and increased inflammation in COVID-19 patients, and possibly increases the risk of SARS-CoV-2 infection." (PMID 35256513, 2022). "In COVID-19 patients, RNH1 expression levels were negatively associated with disease severity and inflammation, suggesting a role for RNH1 in SARS-CoV-2–mediated inflammation and pathology." (PMID 35256513, 2022). "Because our results suggest that RNH1 negatively regulates NFκB and inflammasome activation, we investigated RNH1 levels in COVID-19 patients." (PMID 35256513, 2022). "Strikingly, COVID-19 patients in ICU had less RNH1 expression when compared with COVID-19 patients in general ward (RNH1 mean difference: 0.299; 95% CI : 0.052–0.547, effect size: large [d: 0.961])." (PMID 35256513, 2022). "Further studies with a larger number of patient samples are required to clarify the correlation between RNH1 expression and disease severity in COVID-19 patients." (PMID 35256513, 2022). "We found a significant decrease in RNH1 protein expression in ICU COVID-19 patients compared with COVID-19 general ward patients." (PMID 35256513, 2022). "Because inflammasomes were involved in SARS-CoV-2 infection–mediated inflammation and pathology we also studied the role of RNH1 in COVID-19." (PMID 35256513, 2022). "Furthermore, RNH1 protein levels were negatively related with disease severity and inflammation in hospitalized COVID-19 patients." (PMID 35256513, 2022). "We showed that the expression of RNH1 protein is decreased in lung sections of patients with COVID-19 compared with patients who died from non-viral causes." (PMID 35256513, 2022). "To further support these findings, we analysed RNH1 expression in lung sections of patients from an independent study in the UK who deceased either from COVID-19 (n = 8) or from non-viral causes (n = 13)." (PMID 35256513, 2022). "We propose that RNH1 is a new inflammasome regulator with relevance to COVID-19 severity." (PMID 35256513, 2022). "In line with the data above, RNH1 expression is largely absent in the lungs of deceased COVID-19 patients, whereas patients who succumbed to non-viral causes did show RNH1 staining in infiltrating cells in the lung." (PMID 35256513, 2022). "Therefore, it is unclear what drives the reduced expression of RNH1 in severe COVID-19 pathology." (PMID 35256513, 2022). "Furthermore, RNH1 expression is largely absent in the lungs of deceased patients with COVID-19 compared with patients who succumbed to non-viral causes." (PMID 35256513, 2022). "Interestingly, we also found that RNH1 expression in buffy coat and lung biopsies is negatively related with SARS-CoV-2–mediated severity and inflammation in COVID-19 patients." (PMID 35256513, 2022). "Buffy coat samples from critically ill COVID-19 patients admitted to the intensive care unit (ICU) (n = 17) and COVID-19 patients admitted to general COVID-19 ward (n = 11 patients) were analysed for RNH1 protein expression by Western blot (see the Materials and Methods section for details)." (PMID 35256513, 2022). "Second, our studies have investigated the expression of RNH1 in COVID-19 patients at admission stage but not at other time points, so we do not know how the expression of RNH1 could affect the progression of the disease over time." (PMID 35256513, 2022). "The decreased RNH1 expression in patients admitted to ICU is unlikely to reflect leukocyte numbers because leukocyte numbers were rather increased in ICU patients compared with general ward COVID-19 patients." (PMID 35256513, 2022).
glioblastoma (1 paper, 2017). The most malignant astrocytic tumor (WHO grade IV). "A total of 5 key DNA repair genes, CDK7, DDB2, RNH1, RFC2 and FAH, were screened to be significantly related to the prognosis of glioblastomas (p = 9.74e−05)." (PMID 28938550, 2017).
kidney injury (1 paper, 2024). Trauma to the kidney. "Ribonuclease inhibitor 1 (RNH1), a ribonuclease (RNase) inhibitor, emerged as a potential biomarker for acute kidney injury and mortality in thoracoabdominal aortic aneurysm patients." (PMID 38951571, 2024).
liver cancer (1 paper, 2022). An epithelial or non-epithelial malignant neoplasm that arises from the liver. "For RNH1, we found that expression of the Neanderthal allele was significantly higher than the modern human allele in liver cancer compared to unaffected liver." (PMID 36503519, 2022). "The two other genes, RARS1 and RNH1, have shown to be involved in other cancers, but not explicitly liver cancer." (PMID 36503519, 2022).
lung carcinoma (1 paper, 2023). "In this study, we have demonstrated that the lung cancer cell-monocyte cross-talk modulates the secretion of IFI30, RNH1, CLEC3B, VCAN, IGFBP2, C2 and TUBB4B favoring tumor growth and metastasis." (PMID 37784035, 2023). "In conclusion, this study identifies IFI30, RNH1 and CLEC3B, VCAN, IGFBP2, C2, TUBB4B as the proteins secreted by lung carcinoma cells and monocytes respectively as a result of their mutual interaction." (PMID 37784035, 2023).
lymph node metastasis (1 paper, 2024). "S2, RNH1 expression was significantly correlated with primary tumor, lymph node metastasis, clinical stages and TNM stages." (PMID 38783241, 2024).